CRCT1 (cysteine rich C-terminal 1)
Synonyms: C1orf42; NICE1; NICE-1
Tractability: No criterion of Open Targets' tractability assessment is met for any kind of drug.
Gene: Protein-coding gene on chromosome 1 (152,514,482 to 152,516,008, forward strand). Ensembl gene ENSG00000169509.
Gene Ontology:
Molecular function: protein binding
Genetic constraint (gnomAD): Loss-of-function variants: 1 observed, 0.93 expected, observed/expected ratio (o/e) 1.07, 90% interval 0.27 to 1.9. That is too few expected variants to judge how well the gene tolerates losing a copy. Missense variants: 160 observed, 106.62 expected, observed/expected ratio (o/e) 1.5, 90% interval 1.32 to 1.71. Synonymous variants: 86 observed, 51.55 expected, observed/expected ratio (o/e) 1.67, 90% interval 1.4 to 1.93.
Homologues: Orthologues: chimpanzee CRCT1 (99% identical), macaque CRCT1 (97% identical), pig CRCT1 (74% identical).
Diseases named in the same sentence as CRCT1 in open-access papers:
CRCT1 is named in the same sentence as 10 diseases in open-access papers, as found by Europe PMC text mining. Sharing a sentence is not in itself a finding about the gene and the disease. The quoted sentences say what the papers report.
Alzheimer disease (1 paper, 2016). A progressive, neurodegenerative disease characterized by loss of function and death of nerve cells in several areas of the brain leading to loss of cognitive function such as memory and language. "Indeed, the role of CRCT1 in Alzheimer’s disease (AD) has been previously studied in mouse models." (PMID 27094739, 2016).
diabetes (1 paper, 2012). "Crct1 (cysteine-rich C-terminal protein 1) and Mmp1a (matrix metallopeptidase 1a, interstitial collagenase) expression levels were also modulated by diet only in normal pregnancies, but diabetes had an effect in dams fed the breeder diet." (PMID 22701643, 2012).
esophageal squamous cell carcinoma (1 paper, 2023). Esophageal squamous cell carcinoma (ESCC) is a type of esophageal carcinoma (EC) that can affect any part of the esophagus, but is usually located in the upper or middle third. "CRCT1 was reported to display tumor-suppressive actions toward esophageal squamous cell cancer." (PMID 37370814, 2023).
gingivitis (1 paper, 2022). A disorder involving inflammation of the gums; may affect surrounding and supporting structures of the teeth. "This review identified that exRNA has the greatest diagnostic potential, with four biomarkers (SPRR1A, lnc-TET3-2:1, FAM25A, CRCT1) displaying sensitivity of >71% and specificity of 100% in the assessed samples (p < 0.001) for gingivitis." (PMID 35453967, 2022).
mucoepidermoid carcinoma (1 paper, 2023). A carcinoma morphologically characterized the presence of cuboidal mucous cells, goblet-like mucous cells, squamoid cells, cystic changes, and a fibrotic stromal formation. "While CRCT1 was found to be fused with MAML2 in mucoepidermoid carcinomas, as in mucoepidermoid carcinomas elsewhere in the body, YAP1 was identified as the fusion partner of MAML2 in metaplastic thymomas and KMT2A in type B2 and B3 thymomas." (PMID 38067300, 2023).
tumor (4 papers, 2022 to 2025). "A tumor-suppressivecapability for CRCT1 may be linked to its role in promoting cornification,a form of terminal differentiation and apoptosis required for theformation of the outermost skin barrier." (PMID 41181894, 2025). "Of the six genes (IGF2BP1, GPRC6A, IL37, CRCT1, SEMG1, and PSG7) for which we analyzed the differential expression between tumor tissues and healthy tissues in TCGA, four genes (CRCT1, PSG7, IL37, and IGF2BP1) showed notable differences." (PMID 36276966, 2022). "Collectively, the evidence suggests that HRNR, CRCT1, KPRP, and FLG2 promote cornification, which might underlie their potential tumor-suppressive action in relation to BC (see Discussion for details)." (PMID 37370814, 2023). "Given that these BCs harbor 1q21.3 amplification and the increased copy numbers of HRNR, FLG2, CRCT1 and KPRP genes, these recurrent BCs are likely vulnerable to these genes-derived tumor suppressions." (PMID 37370814, 2023). "Three genes were established as tumor suppressors and eight were novel to BC, including HNRN, KPRP, CRCT1, and FLG2." (PMID 37370814, 2023). "In addition to possessing tumor-suppression functions, these taxifolin-induced genes (HRNR, FLG2, CRCT1, and KPRP) reside in 1q21.3 and are coamplified in recurrent BCs with 1q21.3 amplification." (PMID 37370814, 2023).
cancer (3 papers, 2021 to 2023). A tumor composed of atypical neoplastic, often pleomorphic cells that invade other tissues. "Most of the genes showed an increase in gene expression during the stages of cancer, particularly in the last two stages, except for NDRG2, FAM3D, KRT78, SLURP1, MUC21, and CRCT1, which showed a significant drop in gene expression compared to normal tissue." (PMID 37917867, 2023). "The potential contribution of taxifolin to HRNR, FLG2, CRCT1, KPRP and other tumor suppressor gene expressions in BC via its impact on cell metabolism is indeed intriguing, considering that metabolic alterations are a typical feature of cancer cells." (PMID 37370814, 2023).
CRCT1 also shares sentences with these, for which no sentence is quoted: cervical cancer (2 papers); breast carcinoma (1); thymoma (1).